AREG (amphiregulin)
Diseases named in the same sentence as AREG in open-access papers (continued):
Sharing a sentence is not in itself a finding about the gene and the disease.
ischemic stroke (3 papers, 2018 to 2023). A stroke disorder caused by obstruction of blood flow to the brain, due to thrombotic (local blood clot formation) or embolic (due to a blood clot or other material traveling from another site) event. "Similarly, AREG deficient Tregs had a parallel phenotype and was rescued with intraventricular administration of exogenous AREG in a mouse model of ischemic stroke." (PMID 37197653, 2023). "Brain Treg also suppress neurotoxic astrogliosis through secretion of the low-affinity epidermal growth factor receptor ligand amphiregulin (AREG), as observed in ischemic stroke mouse models." (PMID 32131483, 2020). "In support of the interpretation of elevated amphiregulin in human blood prior to hemorrhagic transformation of ischemic stroke, the deleterious effect of ErbB/EGFR signaling has been demonstrated when HB-EGF is excessively expressed." (PMID 29342116, 2018). "In human ischemic stroke patients, it has been demonstrated that systemic blood samples collected prior to hemorrhagic transformation have revealed a significant increase of amphiregulin, one of the EGFR/ErgB1 ligands." (PMID 29342116, 2018).
liver disease (3 papers, 2014 to 2024). "We found serum AREG levels in HCC patients to be significantly higher than that of patients with benign liver disease and normal controls (P < 0.01)." (PMID 24860833, 2014). "That hepatic ILC2s can express AREG has also been shown in patients with various liver diseases." (PMID 38571949, 2024). "Their secretion of IL-13 and amphiregulin suggests they may be recruited to promote resolution and repair and thereby they may contribute to ongoing fibrogenesis in liver disease." (PMID 29261670, 2017).
metastatic tumors (3 papers, 2015 to 2022). "AREG potently enhances the malignant behavior of various primary and metastatic tumors." (PMID 34830209, 2021). "Moreover, for the first time, AREG was identified to promote in vivo tumor metastasis and reverse miR-34a-imposed metastasis defects, indicating that AREG is the key determinant in the maintenance of metastatic properties of HNSCC, and a potential therapeutic target for metastatic tumor." (PMID 25762634, 2015).
nonalcoholic steatohepatitis (3 papers, 2015 to 2023). "It was recently reported that AREG expression was enhanced in the hepatic stellate cells in both mice fed a methionine choline-deficient (MCD) diet and in severe human nonalcoholic steatohepatitis." (PMID 37868614, 2023). "AREG expression was also enhanced in the hepatic stellate cells of mice fed with the MCD diet and of severe human nonalcoholic steatohepatitis." (PMID 37868614, 2023).
Obesity (3 papers, 2020 to 2022). Accumulation of substantial excess body fat. "Future studies will be required to determine if selective inhibition of amphiregulin expression could provide a therapeutic option to limit the detrimental consequences of obesity." (PMID 35948530, 2022).
renal fibrosis (3 papers, 2021 to 2025). A final common manifestation of a wide variety of chronic kidney diseases characterized by glomerulosclerosis and tubulointerstitial fibrosis. "In animal models of renal fibrosis, AREG inhibition attenuates the expression of inflammatory cytokines and adhesion molecules." (PMID 37868614, 2023). "The hematoxylin and eosin, Masson’s trichrome, and immunohistochemical staining results showed that SAMiRNA-AREG decreased renal fibrosis, AREG expression, and epidermal growth factor receptor (EGFR) phosphorylation in the UUO- and AD-induced models." (PMID 33500443, 2021). "Recently, AREG has been identified as an important factor for myofibroblast proliferation in many diseases, and AREG combined with EGFR amplified renal fibrosis in the proximal tubules." (PMID 33500443, 2021). "The novel inhibition pathway of the AREG gene using SAMiRNA-AREG had reno-protective effects by ameliorating renal fibrosis and inflammation." (PMID 33500443, 2021). "We next determined whether SAMiRNA-AREG regulated EGFR phosphorylation, which is a critical mediator of renal fibrosis and acts as a receptor of AREG." (PMID 33500443, 2021).
skin tumor (3 papers, 2021 to 2026). "Second, there is overwhelming evidence supporting a role for AREG in tumour development, as AREG is upregulated in numerous neoplasms, including head, neck, lung, breast, stomach, liver, colon, prostate, bladder and skin tumours, and capable of self‐sufficient growth and survival signals." (PMID 34382262, 2021). "Transgenic AREG overexpression in keratinocytes leads to inflammatory epidermal hyperplasia without spontaneous development of skin tumors, suggesting that aberrant EGFR signaling is not sufficient to drive tumorigenesis." (PMID 33497366, 2021).
tylosis (3 papers, 2017 to 2018). "We generated mice carrying the human tylosis disease mutation p.P189L and show that enhanced amphiregulin secretion underlies tylosis." (PMID 28655741, 2017). "Also, more recently, we showed in mice that AREG underlies the hyperproliferative skin disease tylosis and that loss of AREG restores the normal skin phenotype in a mouse model of human tylosis." (PMID 29632822, 2018). "Collectively, our data suggest that RHBDF2 plays a critical role in regulating EGFR signaling and its downstream events, including development of tylosis, by facilitating enhanced secretion of AREG." (PMID 28655741, 2017). "Further, substantial evidence implicates the involvement of AREG-induced constitutive activation of the EGFR pathway in tylosis." (PMID 28655741, 2017). "We generated a mouse model of human tylosis and show that GOF mutations in RHBDF2 cause tylosis by enhancing the amount of amphiregulin (AREG) secretion." (PMID 28655741, 2017). "Collectively, these studies suggest that AREG is a functional driver of tylosis; however, the role of the immune system and the effect of the genetic background on the tylosis phenotype remain unknown." (PMID 29116018, 2017). "In addition, we show that genetic ablation of AREG attenuates skin disease in the Rhbdf2P159L/P159L mouse model of human tylosis." (PMID 28655741, 2017). "Together, our data strongly suggest that inhibition of AREG could have potential therapeutic value in the treatment of tylosis." (PMID 28655741, 2017). "In addition, based on our previous findings showing that increased AREG levels mediate the Rhbdf2cub phenotype, and the findings of the present study, we propose that tylosis therapies should be targeted toward inhibition of AREG specifically in the skin." (PMID 29116018, 2017). "The curly bare mouse model of tylosis, carrying a GOF mutation in the Rhbdf2 gene (Rhbdf2cub), presents with epidermal hyperplasia and shows accelerated cutaneous wound-healing phenotype through enhanced secretion of the epidermal growth factor receptor family ligand amphiregulin." (PMID 29116018, 2017). "Thus, targeting AREG could have therapeutic benefit in the treatment of tylosis." (PMID 28655741, 2017). "The role of RHBDF2 in enhancing amphiregulin (AREG) secretion, and consequently activating the epidermal growth factor receptor (EGFR) pathway, has significance for the skin disease tylosis." (PMID 28655741, 2017).
allergies (2 papers, 2019 to 2020). "Among the several novel transcriptomes identified, AREG was verified through validation, and is thus proposed as a possible therapeutic target for allergic diseases." (PMID 33207814, 2020). "Our validation study showed increased AREG mRNA expression in Der p 1-treated THP-1-derived DCs and higher protein expression in DCs harvested from patients with allergies compared to the control." (PMID 33207814, 2020). "In validation experiments, amphiregulin (AREG) showed consistent results with transcriptome sequencing data, with increased mRNA expression in THP-1-derived DCs after Der p 1 stimulation and higher protein expression in myeloid DCs obtained from patients with allergies." (PMID 33207814, 2020).
Arthritis (2 papers, 2021 to 2023). Inflammation of a joint. "Among them, AREG, BPI and TAP1 genes showed an increased expression in arthritis participants." (PMID 38022684, 2023).
atherosclerosis (2 papers, 2019 to 2025). A disease characterized by the build-up of fatty material and calcium deposition in the arterial wall resulting in partial or complete occlusion of the arterial lumen. "Therefore, the KGs in the early stages of atherosclerosis are IL1B and AREG." (PMID 40824771, 2025).
autism (2 papers, 2021 to 2023). Persistent deficits in social interaction and communication and interaction as well as a markedly restricted repertoire of activity and interest as well as repetitive patterns of behavior. "EGF and AREG have been identified as potential genetic risk factors for autism." (PMID 33445520, 2021).
Autoimmunity (2 papers, 2023 to 2024). The occurrence of an immune reaction against the organism's own cells or tissues. "The first being that the effects of amphiregulin during autoimmunity were studied using mice that have a global deletion of amphiregulin." (PMID 37903947, 2023). "Therefore, the interplay between PGE2-driven AREG production and AREG-mediated TGF-β activation via integrins highlights a complex regulatory network essential for immune suppression, where disruption can lead to uncontrolled immune responses and autoimmunity." (PMID 39156643, 2024). "Why the amphiregulin/EGFR pathway is not effective in supporting beta cell function is unclear, but could point to another reason for the inability of Tregs to effectively control anti-beta cell autoimmunity." (PMID 37903947, 2023).
Chronic colitis (2 papers, 2025). A chronic inflammatory disease of the large intestine (colon, cecum and rectum). "Recently, the research group induced chronic colitis in both wild-type and Areg-knockout mice, demonstrating the role of AREG as a key regulator bridging tissue injury to the development of intestinal fibrosis." (PMID 40868999, 2025).
chronic lung disease (2 papers, 2017 to 2018). According to the definitions of the American and British Thoracic Societies, including pulmonary functional tests, X-rays, and CT scans for items such as fibrosis, bronchiectasis, bullae, emphysema, nodular or lymphomatous abnormalities. "So far, polymorphisms associated with the ADAM17, AREG, or EGFR genes have not been directly linked to chronic lung disease, but that may be due to limitations of the studies." (PMID 29540993, 2018).
endometrial cancer (2 papers, 2008 to 2017). Primary or metastatic malignant neoplasm involving the endometrium (mucous membrane that lines the endometrial cavity). "In human endometrial cancer cell line Sawano, mRNAs of AREG and TEAD1 were markedly upregulated by the loss of LSR." (PMID 28071680, 2017). "In endometrial cancer tissues, downregulation of LSR and upregulation of AREG were observed together with malignancy, and Yes-associated protein (YAP) was present in the nuclei." (PMID 28071680, 2017). "In the present study, we first found that the loss of tricellular tight junction protein LSR promoted the invasion and migration of human endometrial cancer cells via upregulation of TEAD/AREG." (PMID 28071680, 2017). "Furthermore, LSR expression decreased and that of AREG increased in G2 and G3 endometrial cancers compared to G1." (PMID 28071680, 2017). "Our preclinical findings, however, do suggest that increased expression of EGFR ligands such as amphiregulin, TGF-α, epiregulin, or NRG1 may also be associated with sensitivity to lapatinib in endometrial cancer." (PMID 18334972, 2008). "In the present study, in human endometrial cancer tissues, downregulation of LSR and upregulation of AREG were observed together with malignancy." (PMID 28071680, 2017). "The loss of LSR promoted cell invasion and migration via upregulation of TEAD1/AREG dependent on YAP/pYAP and AMOT/Merlin in human endometrial cancer cells." (PMID 28071680, 2017). "Taken together, our findings indicated that the loss of LSR promoted cell invasion and migration via upregulation of AREG dependent on YAP/pYAP and AMOT/Merlin in human endometrial cancer cells." (PMID 28071680, 2017). "In endometrial cancer which was diagnosed as the classic endometrial type I (endometrioid), LSR and AREG were highly expressed in some cancer cells that formed gland-like structures." (PMID 28071680, 2017). "Moreover, endometrial cancer demonstrated significantly higher expression levels of the EGFR ligands TGF-α and amphiregulin compared with normal endometrium." (PMID 18334972, 2008).
eosinophilic esophagitis (2 papers, 2025). Eosinophilic esophagitis (EoE) is a chronic, allergic disease of the esophagus characterized clinically by symptoms of esophageal dysfunction (including vomiting, dysphagia, feeding disorders, food impaction and abdominal pain) which persist after treatment with proton pump inhibitors (PPIs). "Recent studies have revealed important roles for AREG in eosinophilic esophagitis (EoE) and esophageal fibrosis." (PMID 40725192, 2025).
esophageal cancer (2 papers, 2011 to 2017). A primary or metastatic malignant neoplasm involving the esophagus. "Because both EGF and AREG have been implicated in progression of esophageal cancer, it was of interest to examine the involvement of SPHK1." (PMID 21936950, 2011).
glomerulonephritis (2 papers, 2021 to 2024). A renal disorder characterized by damage in the glomeruli. "In a mouse model of glomerulonephritis, it was found that upregulation of AREG plays an important proinflammatory role, by enhancing myeloid cell responses and directing the macrophages toward a pro-inflammatory M1 phenotype whereas AREG knockout mice displayed considerable improvement in disease." (PMID 39234105, 2024).
graft versus host disease (2 papers, 2022 to 2025). An immune system disorder that occurs after allogeneic hematopoietic stem cell transplant and is a reaction of donor immune cells against host tissues. "Contrary to the protective roles, AREG was highly expressed in intestinal biopsies of pediatric patients with IBD and severe graft-versus-host disease, which suggests that AREG staining could be used as a marker for severe inflammation." (PMID 40725192, 2025).
heart failure (2 papers, 2021 to 2024). Inability of the heart to pump blood at an adequate rate to meet tissue metabolic requirements. "We found that the expression of both HBEGF and AREG was significantly higher in circulating monocytes of heart failure patients carrying DNMT3A CHIP-driver mutations compared to No-CHIP carriers." (PMID 38242884, 2024). "Within the Ly6clow group of macrophages that proliferates 1 week after TAC, on the other hand, it is the CCR2+ macrophages that are affected by the absence of CD8+T cells and that produce the growth factors (IGF-1, AREG, OSM) which are supposed to be involved in reduced heart failure." (PMID 34745139, 2021).
Infertility (2 papers, 2014 to 2016). "The lack of complete infertility led to the speculation that this phenotype was due to compensation by elevated expression of the ligand amphiregulin (Areg)." (PMID 24945252, 2014).
lymph node metastases (2 papers, 2015 to 2017). "The results also indicated that high Trop2 and AREG protein coexpression was associated with TNM stage, lymph node metastases and distant metastases." (PMID 28256068, 2017). "On the other hand, 11 samples co-expressed increased miR-34a and decreased AREG, 3 of which (27.3%) exhibited lymph node metastasis." (PMID 25762634, 2015).
mucoepidermoid carcinoma (2 papers, 2016 to 2018). A carcinoma morphologically characterized the presence of cuboidal mucous cells, goblet-like mucous cells, squamoid cells, cystic changes, and a fibrotic stromal formation. "The results from in vitro and in vivo studies have demonstrated that aberrantly activated AREG-EGFR signaling is required for CRTC1-MAML2-positive MEC (mucoepidermoid carcinoma) cell growth and survival." (PMID 27391842, 2016).
Myocardial fibrosis (2 papers, 2022 to 2025). "AREG knockout can reduce AngIIinduced myocardial fibrosis in mice." (PMID 35996142, 2022). "Notably, overexpression of AREG+ Tregs stimulates robust neovascularization post-AMI, reduces myocardial fibrosis, and further enhances cardiac function." (PMID 40495143, 2025).
Neisseria gonorrhoeae Infection (2 papers, 2011). "Neisseria gonorrhoeae infection induces expression, processing and release of amphiregulin, an epidermal growth factor (EGF) family member that is anti-apoptotic." (PMID 21998584, 2011). "No change in amphiregulin mRNA levels was detected in vaginal epithelial VK2/E6E7 cells after gonococcal infection." (PMID 21298020, 2011). "The upregulation was also seen in HEC-1-B cells, with a 15-fold upregulation of amphiregulin mRNA after 6 hours of gonococcal infection but not after infection with N. lactamica or E. coli." (PMID 21298020, 2011).
pancreatic adenocarcinoma (2 papers, 2012 to 2026). "AREG's discovery as a potential cyst fluid biomarker arose from observations of increased Anterior Gradient 2 (AGR2) gene expression among pancreatic adenocarcinomas." (PMID 22333441, 2012).
Pancreatic cysts (2 papers, 2012 to 2023). A cyst of the pancreas that possess a lining of mucous epithelium. "AREG was found to be predictive of high-risk IPMN in a serum biomarker panel based on antibody microarray technology and has also been detected in pancreatic cyst fluid." (PMID 36930707, 2023). "In this study, the diagnostic utility of the secreted epidermal growth factor receptor ligand, amphiregulin (AREG), was explored as a cyst fluid biomarker for the presence of malignancy in pancreatic cysts." (PMID 22333441, 2012).
pancreatitis (2 papers, 2016 to 2023). Inflammation of the pancreas. "The present study therefore establishes for the first time the induction of four molecules, AGR2, EGFR, YAP1, and AREG, each of which have been individually associated with tissue regeneration in other organs, but are now all activated during pancreatitis." (PMID 27764193, 2016). "Thus, consistent with previous work, pancreatitis-associated AGR2 expression initiates EGFR cell signaling, activates YAP1, and induces AREG expression." (PMID 27764193, 2016). "EGFR signaling during pancreatitis was significantly reduced by AG1478 as determined by cell surface phosphorylated EGFR, nuclear EGR1, and AREG expression." (PMID 27764193, 2016).
polycystic ovarian syndrome (2 papers, 2022 to 2025). "In addition, the concentration of AREG was lower in polycystic ovarian syndrome (PCOS) follicular fluid than in normal follicular fluid." (PMID 36476625, 2022).
rectal cancer (2 papers, 2019 to 2024). A primary or metastatic malignant neoplasm that affects the rectum. "We identified 15 proteins associated with colorectal, colon, and/or rectal cancer, such as AREG and GDF15 [1.30 (1.19–1.42) and 1.32 (1.20–1.45)]." (PMID 38750076, 2024).
Sjögren’s syndrome (2 papers, 2021 to 2024). "Furthermore, abnormal expression of the ADAM17/AREG axis has been demonstrated in salivary gland epithelial cells (SGECs) in patients with Sjögren’s syndrome." (PMID 39768182, 2024). "The activation of the ADAM17/AREG/EGFR/ERK1/2 pathway leads to an increased release of pro-inflammatory cytokines in the salivary glands, augmenting the inflammatory status that characterizes the autoimmune rheumatic disease Sjögren’s syndrome (SS)." (PMID 39768182, 2024).
skin cutaneous melanoma (2 papers, 2014 to 2026). "RNA‐seq data from skin cutaneous melanoma (SKCM) in The Cancer Genome Atlas (TCGA) was analyzed to assess the clinical relevance of AREG and its association with PGE2 synthesis." (PMID 41082397, 2026).